ANK2 (ankyrin 2)
Diseases named in the same sentence as ANK2 in open-access papers (continued):
Sharing a sentence is not in itself a finding about the gene and the disease.
epilepsy (continued). "With the increased availability of whole exome sequencing, the diagnosis of ANK2‐related epilepsies may increase." (PMID 39962910, 2025). "Notably, most cases of ANK2‐related epilepsy are self‐limited and pharmaco‐responsive, which suggests that it is likely to be underdiagnosed." (PMID 39962910, 2025). "Unlike previously reported cases of ANK2‐related epilepsy, which typically involved de novo mutations, our family appears to be dominantly inherited." (PMID 39962910, 2025). "Furthermore, a correct genetic diagnosis of ANK2‐related epilepsy will initiate close cardiac surveillance to avoid the potential sudden death risk of this disorder." (PMID 39962910, 2025). "Epilepsy‐related ANK2 variants are all LOF variants, including nonsense, frameshift, and splicing variants while the pathogenic missense variants are all associated with CV phenotype." (PMID 39962910, 2025). "Clinical and genetic information of patients with ANK2‐related epilepsy." (PMID 39962910, 2025). "There are different groups of variants associated with different phenotypes; one group of ANK2 variants is primarily associated with a broad cardiac phenotype, another is associated with neurological diseases including ASD and epilepsy, and others are linked to metabolic perturbations." (PMID 35990955, 2022). "Finally, we use our analysis to prioritize new candidate genes for epilepsy (i.e. ANK2, CACNA1E, CACNA2D3, GRIA2, DLG4) for further validation." (PMID 33441621, 2021). "Other ANK2 variants may contribute to risk for ASD and epilepsy." (PMID 35990955, 2022). "Beyond the heart, ANK2 is emerging as an important gene in neurological conditions, including ASD and epilepsy." (PMID 35990955, 2022). "Although epilepsy was not initially identified in ANK2‐related disorders, it can be the main presentation in some cases, like our family." (PMID 39962910, 2025). "Patients with ANK2‐related ASD and epilepsies may benefit from intensive cardiac monitoring and preventive measures if prompt genetic diagnosis can be achieved." (PMID 39962910, 2025). "Given that ANKB is also highly expressed in neurons and involved in maintaining the organization of ion channels and receptors in the synapses, it is surprising that ANK2‐related epilepsies were reported scarcely." (PMID 39962910, 2025). "Given the mild epilepsy phenotype without obvious ASD and cardiac manifestations, we believed ANK2‐related epilepsies may be under‐recognized and underdiagnosed." (PMID 39962910, 2025). "Considering that KCNQ2 and KCNQ3 turned out to directly contributing to the initiation and progression of epilepsy, our predicted genes ANK1 and ANK2 as the functional components of ankyrins may very probably be epilepsy associated genes, validating our prediction." (PMID 28255556, 2017).
autism spectrum disorder (8 papers, 2018 to 2025). A spectrum of developmental disorders that includes autism, and Asperger syndrome. "Lastly, ANK2 (ankyrin 2) (4q25) plays a key role in cell activation, proliferation, and motility in nervous system development and is associated with autism spectrum disorder." (PMID 40631452, 2025). "NOTCH1, NOTCH2, and ANK2 have also been associated with mental disorders, such as autism spectrum disorder." (PMID 41157308, 2025). "Ankyrin 2 is a high confidence autism spectrum disorder (ASD) gene encoding the spectrin-actin scaffold protein Ankyrin B (AnkB)." (PMID 41176091, 2025). "Variants in the high confident autism spectrum disorder (ASD) gene ANK2 target both ubiquitously expressed 220 kDa ankyrin-B and neurospecific 440 kDa ankyrin-B (AnkB440) isoforms." (PMID 34812142, 2021).
Tinnitus (8 papers, 2022 to 2025). Tinnitus is an auditory perception that can be described as the experience of sound, in the ear or in the head, in the absence of external acoustic stimulation. "A whole exome sequencing study of severe tinnitus reported an enrichment of rare missense variants in several synaptic genes, including ANK2, AKAP9 and TSC2, in a Spanish cohort of Meniere’s Disease (MD) patients with catastrophic tinnitus (N=59)." (PMID 41378354, 2025). "Recent research revealed an overload of missense variants in the ANK2 gene in individuals with severe tinnitus." (PMID 39815069, 2025). "A major gap in understanding is how rare variants in the ANK2 gene contribute to severe tinnitus or inner ear neuron development in MD patients." (PMID 39815069, 2025). "The goal of this study was to generate an iPSC line from a severe tinnitus patient carrying mutations in the ANK2 gene." (PMID 39815069, 2025). "Exome sequencing in tinnitus patients has identified rare variants in ANK2 associated with severe tinnitus." (PMID 39815069, 2025). "This study aims to report the clinical, audiological, and psychometric findings observed in patients with chronic tinnitus and rare variants in the ANK2 gene to define an endophenotype in the carriers of rare variants." (PMID 38507076, 2024). "As a result of such efforts, the ANK2 gene has been associated with severe tinnitus, shedding light on the involvement of membrane trafficking and cytoskeletal protein binding in the pathophysiology of this condition." (PMID 38507076, 2024). "Patients with variants in ANK2 and severe tinnitus have an endophenotype defined by hyperacusis, persistent noise type tinnitus, high frequency hearing loss, and increased AMLR amplitude." (PMID 38507076, 2024). "This study aims to describe the audiological and psychometric profile of patients with chronic tinnitus and rare variants in the ANK2 gene." (PMID 38507076, 2024). "The case series consisted of 12 patients with tinnitus and heterozygous variants in the ANK2 gene, ages between 46 and 72 (57 ± 7.9), ten women, and two men." (PMID 38507076, 2024). "This case series is focused on the analysis of patients with tinnitus extreme phenotype and rare variants in the ANK2 gene, and these results cannot be extended to the general population." (PMID 38507076, 2024). "Patients with ANK2 variants and severe tinnitus exhibit an endophenotype featuring hyperacusis, persistent noise-like tinnitus, high-frequency hearing loss, and decreased amplitudes in AMLR." (PMID 38507076, 2024). "In Spanish patients with MD, using exome sequencing and gene burden analyses, severe tinnitus has been associated with rare missense variants in 24 synaptic genes, including ANK2, TSC2, and AKAP9." (PMID 38254912, 2023). "Individuals with missense variants in known genes described for severe tinnitus such as ANK2, TSC2, and AKAP9 were targeted for specific LSVs overlapping these genes." (PMID 36450758, 2022). "We also found some rare variants previously reported in genes associated with tinnitus such as ANK2, AKAP9 and TSC2." (PMID 36450758, 2022). "This approach has led to the identification of the ANK2 gene as a potential candidate, linking membrane trafficking and cytoskeletal protein binding to the pathophysiology of severe tinnitus." (PMID 39815069, 2025). "In this study, we generated a cellular model derived from patients with MD and tinnitus to explore the role of ANK2 in auditory-evoked responses and neural development, comparing it with a control cell line." (PMID 39815069, 2025). "We generated a hiPSC line derived from a patient with severe tinnitus carrying a missense mutation in the ANK2 gene (4:114,294,537 G/A) using a non-integrating Sendai virus method for reprogramming." (PMID 39815069, 2025). "Moreover, gene burden analyses in sequencing data from Spanish and Swede patients with severe tinnitus have identified and replicated ANK2, AKAP9, and TSC2 genes." (PMID 38334885, 2024).
Tinnitus (continued). "Although more individuals with variants in ANK2 need to be studied, we cannot rule out an effect of ANK2 in hearing or vestibular loss in addition to tinnitus." (PMID 38507076, 2024). "Although several rare missense SNVs were reported in MD and severe tinnitus, including ANK2, TSC2, and AKAP9 genes, these variants do not explain the presence of other comorbidities with a higher prevalence." (PMID 38254912, 2023). "Previous research revealed the presence of genes related with axonal branching (ANK2, AKAP9, and TSC2) in tinnitus patients." (PMID 38562529, 2024). "Although animal models have explored ANK2’s role in acoustic trauma and neuronal dysfunction, its involvement in auditory-evoked responses and neural development, particularly in tinnitus, has not been studied in human cellular models." (PMID 39815069, 2025).
schizophrenia (7 papers, 2017 to 2026). A major psychotic disorder characterized by abnormalities in the perception or expression of reality. "To complement the robustness of finding therapeutic relevant gene targets, we compared with evidence from GWAS and found three schizophrenia-associated eQTL genes in the two main clusters of the PPI networks (i.e., PDCD10 and AKT3 in cluster 1, ANK2 in cluster 2)." (PMID 35886854, 2022). "The protein-protein interaction (PPI) networks found two main clusters having schizophrenia expression quantitative trait loci (eQTL) genes such as PDCD10, ANK2, and AKT3, suggesting further investigation on these genes as potential novel treatment targets." (PMID 35886854, 2022). "Some schizophrenia eQTL genes such as PDCD10, ANK2 and AKT3 with highly connected functions to these pathways should be further investigated to find out how they and their related pathways are involved with the disease, which might potentially enable the finding of novel treatment targets." (PMID 35886854, 2022). "While the function of ANK2 in brain has not been as well researched as ANK3, ANK2 is a schizophrenia-related eQTL gene." (PMID 35886854, 2022).
breast carcinoma (6 papers, 2018 to 2024). "Concerning ANK2 expression, it has been found to be downregulated in breast cancer and colon adenocarcinoma, which was consistent with the findings of our pan-cancer analysis." (PMID 36539782, 2022). "In terms of relapse, some breast cancer samples in the poor prognosis group revealed significantly higher ANK2 expression, indicating that ANK2 may be related to personalized relapse mechanism." (PMID 32770099, 2020). "It is of note that other members of the ankyrin family, namely ANK1 and ANK3, have been shown to be overexpressed in multiple human cancers including breast cancer, while ANK2 overexpression has been shown in pancreatic cancer where it contributed to the malignant phenotype." (PMID 33218035, 2020). "Four genes (six associations: BRCA1, BRCA2, and ANK2 in ovarian cancer, BRCA1, BRCA2, and ATM in breast cancer) were significant in at least one individual cancer type (FDR = 0.2, referred to as ‘individual cancer ALFRED genes’) and all four genes were also significant in the pan-cancer analysis." (PMID 29973584, 2018). "Additionally, ANK2 showed significant hypermethylation in the plasma cfDNA of canine mammary tumors, indicating it could be a possible liquid biopsy biomarker as well." (PMID 38977697, 2024). "Our findings were further validated using qRT-PCR, western blotting and immunohistochemistry which show decreased expression of NLGN3, MAML2, ANK2, and SYNE1 in breast cancer cell lines as MCF7 and MDA-MB-231 as compared to control cell line MCF10A." (PMID 38977697, 2024). "Collectively, the in vitro findings suggest the role of ANK2 and NLGN3 in breast tumorigenesis suggesting it may be a potential drug target for breast cancer therapeutics." (PMID 38977697, 2024). "The unpaired student’s t-test showed the decrease in protein expression of ANK2, SYNE1 and NLGN3 was significant in the cancer cell lines MDA-MB-231 (p-value < 0.05) when compared with control MCF10A and decrease in protein expression of SYNE1 was significant in MCF7 breast cancer cell line." (PMID 38977697, 2024).
catecholaminergic polymorphic ventricular tachycardia (6 papers, 2013 to 2025). "Variations in genes implicated in cardiac calcium signaling have been shown to cause a number of arrhythmia syndromes, including long-QT syndrome 4 (ANK2) and 8 (CACNA1C), Brugada syndrome (CACNA1C) and catecholaminergic polymorphic ventricular tachycardia (RyR2)." (PMID 27857207, 2016).
colorectal cancer (6 papers, 2019 to 2026). A primary or metastatic malignant neoplasm that affects the colon or rectum. "Overexpression of lncRNA ZNF667-AS1 in colorectal cancer inhibited cell propagation, migration, and metastasis by controlling the ANK2/JAK2 signaling pathway." (PMID 35813862, 2022). "Similarly, ZNF667-AS1 suppressed the progression of colorectal cancer through affecting ANK2/JAK2 axis." (PMID 39425009, 2024). "However, other studies found that ANK2 gene expression was downregulated in colorectal cancer and thyroid cancer, which corresponds to what we found in this study." (PMID 33218035, 2020).
Ventricular arrhythmia (6 papers, 2007 to 2025). "Ank2+/− mice display increased susceptibility to atrial and catecholamine-induced ventricular arrhythmias and sudden death, as well as, premature senescence and reduced lifespan." (PMID 35990955, 2022). "Finally, beyond LQT and catecholaminergic polymorphic ventricular tachycardia, ANK2 variants have been associated with other forms of ventricular arrhythmia including early repolarization syndrome." (PMID 29163198, 2017). "Recently, the role of ANK2 in arrhythmogenic right ventricular cardiomyopathy (ARVC), a condition characterized by fibrofatty replacement of the myocardium, ventricular arrhythmias, and sudden cardiac death has come to attention." (PMID 35990955, 2022).
channelopathy (5 papers, 2019 to 2024). Channelopathies are a group of diseases caused by the dysfunction of ion channel subunits or their interacting proteins. "NGS revealed the index case was heterozygous for three additional low-frequency variants in channelopathy-associated genes that are more frequent in Latinos: SCN5A p.V1951L (rs41315493), ANK2 p.G2221E (rs185384934) and TRDN p.S80F (rs181287533)." (PMID 38256028, 2024). "Our results suggest potassium channel dysfunction (Kv7.2/3) as a novel pathophysiology underlying Ank2-related ASD, providing support for the increasing importance of channelopathies in ASD57." (PMID 37321992, 2023). "The variants included three channelopathy-associated genes (RYR2, CACNA1C, and ANK2), three HCM- or DCM-associated genes (MYH7, LDB3, and PRKAG2), five ACM-related genes (PKP2, JUP, DSG2, DSP, and TMEM43), and two cardiac transcription factor genes (TBX5 and GATA4)." (PMID 39272661, 2024). "Therefore, Ank2 regulates neuronal excitability by controlling AIS length and density of Kv7, and Kv7 channelopathy is involved in Ank2-related brain dysfunctions." (PMID 37321992, 2023).
pancreatic cancer (5 papers, 2016 to 2023). "ANK2 promotes the growth and invasion of pancreatic carcinoma, and the peptide derived from ANK2 is an effective and specific autophagy inhibitor binding to ATG8." (PMID 36975521, 2023). "Ying and his colleagues proved that ANK2 was overexpressed in pancreatic ductal adenocarcinoma and inhibition of ANK2 reduced invasion ability of pancreatic cancer cells." (PMID 36539782, 2022). "In terms of malignancies, the silencing of ANK2 expression reduced the growth and invasion of pancreatic cancer cells, indicating its potential as a target for therapy." (PMID 32770099, 2020). "SAGE analysis also revealed that ANK2, the ankyrin expressed in lymphocytes, was not differentially expressed in pancreatic cancers." (PMID 27144336, 2016).
atrial fibrillation (4 papers, 2017 to 2025). A disorder characterized by an electrocardiographic finding of a supraventricular arrhythmia characterized by the replacement of consistent P waves by rapid oscillations or fibrillatory waves that vary in size, shape and timing and are accompanied by an irregular ventricular response. "ANK2 encodes ankyrin-B, which interacts with ion channels and transporters and has been associated with congenital long QT arrhythmia syndrome, episodes of atrial fibrillation, and other types of cardiac dysfunction." (PMID 40013929, 2025). "Individuals with select ANK2 loss-of-function variants display atrial fibrillation and/or sinus node dysfunction." (PMID 29163198, 2017). "This extended gene network contained a number of transcription factors (Tbx5, Hand2, Fhl2, and Gata4) and ion/calcium handling genes (Ank2, Cacna2d2, Scn5a, Kcnd2, Kcnj5, Myoz2, Casq2, Csrp3, and Gja3) of interest in the context of atrial fibrillation." (PMID 28720711, 2017).
Anxiety (3 papers, 2022 to 2025). Intense feelings of nervousness, tension, or panic often arise in response to interpersonal stresses. "Our Ank2+/– mice (adult male) show largely normal behaviors, except for modest anxiety-like behavior (decreased open-field center time)." (PMID 37321992, 2023). "Female global Ank2+/– mice also showed largely normal behaviors in locomotor, anxiety-like, social, repetitive, and sensory-motor domains." (PMID 37321992, 2023). "Ank2 cKO leads to behavioral deficits, including hyperactivity, altered anxiety-like behavior, excessive social interaction, impaired social novelty recognition, suppressed repetitive behavior, and juvenile seizure-related death." (PMID 37321992, 2023). "Behaviorally, Ank2-cKO mice showed hyperactivity and anxiety-like behavior in the open-field test but anxiolytic-like behaviors in light-dark and elevated plus-maze tests, likely because of the distinct nature of the anxiogenic stimuli (open space, height, and light)." (PMID 37321992, 2023). "These clusters particularly involved genes related to regulatory subunits of cAMP-dependent protein kinases, such as PRKAR2A, cAMP-responsive element-binding pathway, circadian rhythms, such as CLOCK, ARNT1, CRY2, PER1, and PER2, and anxiety and depression, such as NOTCH1, NOTCH2 and ANK2." (PMID 41157308, 2025).
Bradycardia (3 papers, 2007 to 2022). A slower than normal heart rate (in adults, slower than 60 beats per minute). "Carriers of the balanced translocation, which includes breakpoints transecting ANK2, did not have congenital heart defects but other cardiac features including bradycardia, ventricular ectopy, sinus node dysfunction, and mild left ventricular dysfunction." (PMID 35990955, 2022).
Intellectual disability (3 papers, 2018 to 2025). "Similarly, variants in ANK2 have been identified in individuals with ASD and intellectual disability and it is ranked as a top high confidence ASD gene with one of the highest mutability scores." (PMID 34812142, 2021).
myocardial infarction (3 papers, 2017 to 2024). Gross necrosis of the myocardium, as a result of interruption of the blood supply to the area, as in coronary thrombosis. "There may be hsa_circ_0001147/hsa-miR-204-5p/GPM6A axis, hsa_circ_0004771/hsa-miR-629-3p/SRSF1 axis, hsa_circ_0061276/hsa-miR-629-3p/SRSF1 axis, hsa_circ_ 0045519/hsa-miR-298/ANK2 axis and hsa_circ_0004561 hsa-miR-298/ANK2 axis regulatory relationship involved in myocardial infarction." (PMID 35872921, 2022). "Therefore, there may be hsa_circ_0001147/hsa-miR-204-5p/GPM6A axis, hsa_circ_0004771/hsa-miR-629-3p/SRSF1 axis, hsa_circ_0061276/hsa-miR-629-3p/SRSF1 axis, hsa_circ_0045519/hsa-miR-298/ANK2 axis, and hsa_circ_0004561 hsa-miR-298/ANK2 axis regulatory relationship involved in myocardial infarction." (PMID 35872921, 2022).
Brugada syndrome (2 papers, 2016 to 2017). "For example, human ANK2 loss-of-function variants are associated with a complex array of electrical and structural phenotypes now termed “ankyrin-B syndrome,” whereas alterations in the ankyrin-G pathway for Nav channel targeting are associated with human Brugada syndrome." (PMID 29163198, 2017).
colon adenocarcinoma (2 papers, 2022). "Various potential biomarkers for colon adenocarcinoma initiation and progression and drug targets were identified and discussed, including seven novel markers: ACSL4, ANK2, AMER3, EXOSC1, EXOSC6, GCLM, and TFRC." (PMID 35842572, 2022).